PRKX (protein kinase cAMP-dependent X-linked catalytic subunit)
Description:
Serine/threonine protein kinase regulated by and mediating cAMP signaling in cells. Acts through phosphorylation of downstream targets that may include CREB, SMAD6 and PKD1 and has multiple functions in cellular differentiation and epithelial morphogenesis. Regulates myeloid cell differentiation through SMAD6 phosphorylation. Involved in nephrogenesis by stimulating renal epithelial cell migration and tubulogenesis. Also involved in angiogenesis through stimulation of endothelial cell proliferation, migration and vascular-like structure formation.
Synonyms: PKX1
Tractability: Small molecule: a high-quality ligand is known; it belongs to a druggable protein family. PROTAC: ubiquitination databases record sites on it; a small molecule that binds it is known.
Target class: Kinase; AGC protein kinase PKA family; Protein Kinase; AGC protein kinase group; Enzyme
Gene: Protein-coding gene on chromosome X (3,604,340 to 3,713,649, reverse strand). Ensembl gene ENSG00000183943.
Subcellular location: Cytoplasm; Nucleus
Subcellular location (Human Protein Atlas): Nucleoplasm
Pathways (Reactome):
Disease: ADORA2B mediated anti-inflammatory cytokines production; FCGR3A-mediated IL10 synthesis
Neuronal System: CREB1 phosphorylation through the activation of Adenylate Cyclase
Signal Transduction: PKA-mediated phosphorylation of CREB
Gene Ontology:
Molecular function: cAMP-dependent protein kinase activity; protein binding; ATP binding; protein kinase activity; protein serine kinase activity; protein serine/threonine kinase activity
Biological process: angiogenesis; cell adhesion; cell-substrate adhesion; endothelial cell migration; endothelial cell proliferation; epithelial tube morphogenesis; kidney morphogenesis; myeloid cell differentiation; peptidyl-serine phosphorylation; protein autophosphorylation; regulation of cell adhesion; regulation of cell migration; regulation of epithelial cell differentiation involved in kidney development; adenylate cyclase-activating G protein-coupled receptor signaling pathway
Cellular component: cytoplasm; nucleoplasm; nucleus; cAMP-dependent protein kinase complex; cytosol
Homologues: Orthologues: chimpanzee PRKX (99% identical), macaque PRKX (98% identical), macaque PRKX (94% identical), chimpanzee PRKY (93% identical), dog PRKX (89% identical), pig PRKX (88% identical), tropical clawed frog prkx (80% identical), mouse Prkx (77% identical), zebrafish prkx (74% identical), rat Prkx (67% identical), Drosophila melanogaster Pka-C3 (57% identical), Caenorhabditis elegans F47F2.1 (46% identical). Paralogues in human: PRKACB (48% identical), PRKACA (47% identical), PRKACG (43% identical), PRKG1 (42% identical), PRKG2 (42% identical).
Diseases named in the same sentence as PRKX in open-access papers:
PRKX is named in the same sentence as 22 diseases in open-access papers, as found by Europe PMC text mining. Sharing a sentence is not in itself a finding about the gene and the disease. The quoted sentences say what the papers report.
aortic aneurysm (2 papers, 2016 to 2018). A ruptured aneurysm located in the wall of the proximal portion of the descending aorta proceeding from the arch of the aorta. "Additionally, the implementation of genetic testing to identify genes associated with malformations (ZFYVE9, TIMP1, PRKX, KDM6A) can lead to a higher detection rate of aortic aneurysm formation, congenital urinary malformations and other anomalies." (PMID 29537378, 2018). "We point to candidate genes of comorbidity in TS e.g. congenital urinary malformations (PRKX), premature ovarian failure (KDM6A) and aortic aneurysm (ZFYVE9 and TIMP1)." (PMID 27687697, 2016). "We describe novel candidate genes that could be involved in comorbidity in TS and explain congenital urinary malformations (PRKX), premature ovarian failure (KDM6A), and aortic aneurysm formation (ZFYVE9 and TIMP1)." (PMID 27687697, 2016).
MRKH syndrome (2 papers, 2021). "The present study suggests a possible molecular cause for MRKH syndrome and a role for PRKX in vaginal keratinocyte biology." (PMID 34063745, 2021). "Our study identified the dysregulation of PRKX expression as a possible molecular cause for MRKH syndrome." (PMID 34063745, 2021). "By investigating PRKX dysregulation effects on a model cell line, we contributed toward the identification of a possible molecular cause for MRKH syndrome and highlighted that epigenetics and system biology should always be considered while studying the basis of a complex disease." (PMID 34063745, 2021). "However, despite the need for further studies, we laid the basis to speculate that a general dysregulation of PRKX expression might be one of the possible causes of MRKH syndrome." (PMID 34063745, 2021). "In order to confirm altered PRKX gene expression in MRKH syndrome, as suggested by our recently published work, we extended PRKX mRNA expression analysis to the entire cohort, investigating 34 MRKH patients and a pool of 4 healthy control women." (PMID 34063745, 2021). "Taken together, these results further indicate a role for PRKX in MRKH syndrome determination, which should be confirmed by future in vivo studies." (PMID 34063745, 2021). "In order to establish a correlation between MRKH syndrome phenotype and gene expression pattern, we performed PCA on data from RT-qPCRs for PRKX, MUC1, HOXC8 and GREB1L loci." (PMID 34063745, 2021). "Although we obtained interesting results, we cannot directly correlate PRKX effects on cell migration, EMT induction, and HOX gene expression to MRKH syndrome determination." (PMID 34063745, 2021). "PRKX has never been correlated to female genital tract anomalies before, therefore we decided to deeply explore its molecular and biological function in MRKH syndrome." (PMID 34063745, 2021). "Noteworthy, we found PRKX to be a hub in our MRKH-related network, interacting with proteins functionally involved in cell movement and migration, further supporting a potential role for this gene in MRKH syndrome determination." (PMID 33432050, 2021). "We found altered PRKX mRNA expression throughout our cohort of MRKH patients; therefore, we hypothesised that increased levels of PRKX levels may somehow influence the molecular mechanisms underneath MRKH syndrome determination." (PMID 34063745, 2021).
coronary artery disease (1 paper, 2023). "PRKX was overexpressed in triple-negative breast cancer and downregulated in coronary artery disease which could be a predictor in these diseases." (PMID 36930329, 2023).
esophageal squamous cell carcinoma (1 paper, 2023). Esophageal squamous cell carcinoma (ESCC) is a type of esophageal carcinoma (EC) that can affect any part of the esophagus, but is usually located in the upper or middle third. "Recent evidence suggests that the novel oncogene NRSN2-AS1 is hyperexpressed in esophageal squamous cell carcinoma and OC tissues, and promotes OC cells proliferation and migration via interaction with miR-744-5p to modulate PRKX." (PMID 37875515, 2023).
hearing loss (1 paper, 2021). "PRKX is located on the X chromosome; it is functionally connected to X-linked congenital hearing loss." (PMID 34912812, 2021). "PRKX (ENSP00000262848) is also associated with congenital pediatric hearing loss." (PMID 34912812, 2021).
nasopharyngeal carcinoma (1 paper, 2025). A carcinoma arising from the nasopharyngeal epithelium. "Conversely, reducing FOLR1 levels alters key apoptotic and MAPK pathway genes (BIRC3, caspases, FOS, DUSP1, PRKX, TNFRSF10A), sensitizing taxol-resistant nasopharyngeal carcinoma cells to chemotherapy." (PMID 41439026, 2025).
oral cancer (1 paper, 2020). "In our research, PRKX is overexpressed in invasive OC3‐I5 cells compared to OC3 cells, which imply that PRKX may promote oral cancer migration and proliferation via cAMP signalling in invasive oral cancer cells." (PMID 32672400, 2020).
osteosarcoma (1 paper, 2023). A usually aggressive malignant bone-forming mesenchymal neoplasm, predominantly affecting adolescents and young adults. "More interestingly, the expression of several of these genes, including CHST13, FKBP11, SGMS2, TRPS1, PRKX, SP7, and DNAJC1, were highly associated with osteosarcoma prognosis." (PMID 37457661, 2023).
ovarian carcinoma (1 paper, 2023). A malignant neoplasm originating from the surface ovarian epithelium. "The latest research found that NRSN2-AS1 is significantly overexpressed in ovarian cancer, plays a tumor-promoting role as the sponge of miR-744-5p, and regulates the Wnt/β-catenin signaling pathway via the miR-744-5p/PRKX axis." (PMID 36816914, 2023).
renal agenesis (1 paper, 2021). Renal agenesis (RA) is a form of renal tract malformation characterized by the complete absence of development of one or both kidneys (unilateral RA or bilateral RA respectively), accompanied by absent ureter(s). "Moreover, in our study, ectopic PRKX overexpression seemed to upregulate HOXD13, whose alteration has been linked to syndromes affecting genitourinary development, renal agenesis, and limb malformations such as synpolydactyly and polydactyly." (PMID 34063745, 2021).
testicular disorder (1 paper, 2025). A non-neoplastic or neoplastic disorder affecting the testis. "Patients with 46,XX testicular disorder exhibit a translocation between PRKX and reverse protein kinase Y (PRKY) genes." (PMID 39891056, 2025).
tumor (5 papers, 2009 to 2025). "Moreover, PRKX binds to enzymes such as Pin-1, Magi-1 and Bag-3, which regulate cell differentiation, proliferation, apoptosis and tumor genesis." (PMID 31964936, 2020). "Of these, 8 genes showed a significant decrease in expression in tumor samples with this deletion relative to tumors samples without this deletion: ARSD, ARSE, MXRA5, PRKX, LOC729137, NLGN4X, HDHD1A, and STS." (PMID 19419571, 2009).
infection (1 paper, 2017). The state of being infected such as from the introduction of a foreign agent such as serum, vaccine, antigenic substance or organism. "This pathway was downregulated at 6 h of P. brasiliensis post-infection infection in mouse lung (PADG_07326: serine/threonine-protein kinase PRKX and PADG_07962: MADS box transcription factor Mcm1), which could be related with lower glycan content in yeast cells upon infection." (PMID 28704618, 2017).
PRKX also shares sentences with these, for which no sentence is quoted: Alzheimer disease (1 paper); breast carcinoma (1); glioma (1); Intellectual disability (1); lung carcinoma (1); melanoma (1); premature ovarian failure (1); triple-negative breast carcinoma (1); vitiligo (1).